MIR4785 (microRNA 4785)
Synonyms: hsa-mir-4785; mir-4785
Gene: MicroRNA gene on chromosome 2 (160,407,810 to 160,407,882, reverse strand). Ensembl gene ENSG00000283734.
Homologues: Orthologues: chimpanzee MIR4785 (100% identical), macaque MIR4785 (100% identical).